IGHG1 (immunoglobulin heavy constant gamma 1 (G1m marker))
Diseases named in the same sentence as IGHG1 in open-access papers (continued):
Sharing a sentence is not in itself a finding about the gene and the disease.
Stroke (3 papers, 2016 to 2025). Sudden impairment of blood flow to a part of the brain due to occlusion or rupture of an artery to the brain. "Finally, IGHG1 was found to be a reliable predictor of CR stroke, known to promote tumor expansion and invasion in multiple malignancies." (PMID 40079446, 2025). "We found that tissue containing microglia nodules in MS had significant upregulated Ig genes (IGKC, IGHG1, IGHG2, and IGKV3-15) compared to tissue containing stroke nodules." (PMID 38396116, 2024). "Also, we found significantly upregulated expression of the Ig genes IGKC, IGHG1, IGHG2, and IGKV3-15 in MS nodule NAWM tissue as compared to stroke." (PMID 38396116, 2024). "In the findings of this study, IGHG1 and IGHG3 are first determined in stroke patients’ platelets, these proteins may interact with platelets surface receptors." (PMID 27336623, 2016).
colon cancer (2 papers, 2016 to 2023). "Meanwhile, analysis of B cell DEGs among different tissues revealed that IgG-related gene (IGHG1-4) was highly expressed in colon cancer." (PMID 37675100, 2023).
influenza (2 papers, 2017 to 2024). An acute viral infection of the respiratory tract, occurring in isolated cases, in epidemics, or in pandemics; it is caused by serologically different strains of viruses (influenzaviruses) designated A, B, and C, has a 3-day incubation period, and usually lasts for 3 to 10 days. "Reanalysis of prior PBMC RNA-seq data on influenza vaccine responses in younger adults showed upregulated expression of IGHG1 and IGHG3 at day 7, whereas pneumococcal vaccines upregulated the expression of IGHA2 and IGHG2." (PMID 38182669, 2024). "The use of a pan-IGHG reverse primer allowed amplification of any IgG isotypes, and sequence analysis revealed the use of IGHG1, IGHG3, and IGHG5 isotypes in foals, and IGHG1 and IGHG6 in mares for both KLH- and influenza-specific B cells." (PMID 28520789, 2017). "Influenza-specific IGHG sequences encoded IGHG1 and IGHG6 isotypes, consistent with reports of influenza-specific serum IgGa (encoded by IGHG1) but not IgGT (encoded by IGHG3 and IGHG5) in response to vaccination of adult horses." (PMID 28520789, 2017).
intrahepatic cholangiocarcinoma (2 papers, 2025). A carcinoma that arises from the intrahepatic bile duct epithelium in any site of the intrahepatic biliary tree. "Concurrently, in intrahepatic cholangiocarcinoma (ICC), plasma cells characterised by IGHG1 and JCHAIN, alongside immune cell infiltration, portend improved survival rates." (PMID 41010015, 2025). "In intrahepatic cholangiocarcinoma (ICC), JCHAIN is a core marker of the “plasma cell+” immune infiltration pattern (co-expressed with IGHG1), which correlates with favorable overall survival by enhancing anti-tumor immunity." (PMID 41153653, 2025).
Obesity (2 papers, 2018 to 2026). Accumulation of substantial excess body fat. "In our study, the identified association between obesity and the hypomethylated CpG site cg13074055 near the gene cluster of immunoglobulin heavy constant genes (IGHE/IGHG1/IGH) is interesting in this respect, as it suggests the expression of immunoglobulins to be potentially modified." (PMID 30397228, 2018).
systemic lupus erythematosus (2 papers, 2019 to 2025). An autoimmune multi-organ disease typically associated with vasculopathy and autoantibody production. "In blood samples of systemic lupus erythematosus, an autoimmune disease, IGHG1 was highly expressed in B cells, suggesting that IGHG1 can indirectly or directly affect the interaction between cancer cells and the immune system." (PMID 40566633, 2025).
viral infection (2 papers, 2023 to 2025). "Interestingly, the elevated IgG gene expression was mainly due to IgG1 (IGHG1) and IgG3 (IGHG3), but not IgG2 (IGHG2), which is in line with the presumed IgG1- and IgG3-switched phenotype of T-bet+ B cells both in MS and during viral infections." (PMID 36796230, 2023).
Warthin tumor (2 papers, 2024). An adenoma characterized by an oncocytic, often papillary, epithelial component, dense lymphoid stroma, and cystic spaces. "On the other hand, the protein network detected in Warthin’s tumors (e.g., IGHG1, IGKC, IGHA1, and S100A9) was associated with immunological and inflammatory diseases." (PMID 39684268, 2024).
Autoimmunity (1 paper, 2025). The occurrence of an immune reaction against the organism's own cells or tissues. "While elevated interferon signalling may also suggest automimicry in this cohort of GWI, the downregulation of IGHG1 and IGHV4–59 suggests reduced humoral immune responses and impaired antibody production, not reminiscent of the presence of autoimmunity which is inconsistent in GWI research." (PMID 41337155, 2025).
cardiomyopathies (1 paper, 2021). "Likewise, we found increased protein levels of immunoglobulin (Ig gamma-1 chain C region - IGHG1) in the samples from patients with CCC, DCM and IC when compared to samples from individuals without cardiomyopathies." (PMID 34867990, 2021).
cervical cancer (1 paper, 2014). A primary or metastatic malignant neoplasm involving the cervix. "To further investigate whether IGHG1 deficiency inhibited the TLR4 signaling pathways in cervical cancer cells, we examined nuclear translocation of NF-κB subunit p65 in Hela cells with immunostaining after LPS treatment." (PMID 25179302, 2014). "We examined TLR4 expression in cervical cancer cells after IGHG1 silencing." (PMID 25179302, 2014). "It should be pointed that we selected IGHG1 for the silencing target only rather than IGHG2, IGHG3 and so on because knockdown of endogenous IGHG1 could lead to more significant biological effects than that of others in cervical cancer cells according to our preliminary experiments." (PMID 25179302, 2014).
chronic kidney disease (1 paper, 2014). Impairment of the renal function secondary to chronic kidney damage persisting for three or more months. "Among the proteins in the predictive list are CUBN, IGHG1, CERU, TFRE and A2GL, which are urinary glycoproteins associated with chronic kidney disease." (PMID 25182141, 2014).
diffuse gastric adenocarcinoma (1 paper, 2024). An adenocarcinoma arising from the stomach. "Furthermore, we observed that the expression level of the IGHG1 gene in 13 SRC cases was higher than that in 72 diffuse gastric adenocarcinoma cases, indicating the distinctive significance of IGHG1 (P < 0.05)." (PMID 38898490, 2024).
gastric adenocarcinoma (1 paper, 2021). "The expression of IGHG1 in highly differentiated, moderately differentiated and poorly differentiated gastric adenocarcinoma tissues was higher than that in normal gastric mucosa tissues (P<0.05)." (PMID 33995624, 2021).
glomerulopathies (1 paper, 2023). "Particularly, PZP, IPSP, and IGHG1 also underlined the differences between particular glomerulopathies; the first two are of particular interest, as they distinguish FSGS and MN, unlike any other core protein." (PMID 37110557, 2023).
Hypercholesterolemia (1 paper, 2025). An increased concentration of cholesterol in the blood. "The largest effect on gene expression was observed for IGHG1 which was lower in COPD patients with hypercholesterolemia." (PMID 40287517, 2025).
lung adenocarcinoma (1 paper, 2022). A carcinoma that arises from the lung and is characterized by the presence of malignant glandular epithelial cells. "Among them, CRABP2, KAT2A, BIRC5, ABCC3, PLK1, IGHG1, and EPCAM were upregulated in lung adenocarcinoma samples, while FABP4 was downregulated in lung adenocarcinoma samples." (PMID 35909589, 2022).
lymph node metastasis (1 paper, 2024). "Although no study has specifically investigated the role of these proteins as diagnostic or prognostic biomarkers in any disease, it has been observed that IGHG1 overexpression accelerates malignant cell migration and invasion in vitro and is associated with lymph node metastasis in ovarian cancer." (PMID 38307924, 2024).
melanoma (1 paper, 2019). A malignant, usually aggressive tumor composed of atypical, neoplastic melanocytes. "In contrast, there is evidence for such a model in melanoma, based on the correlation of large hypermutating clonal IgG1 expansions and high IGHG1/MS4A1 ratio with survival (p = 0.006, HR = 0.7), and cytotoxic activity of tumor-specific IgG1 antibodies." (PMID 31665076, 2019).
Meniere disease (1 paper, 2014). A disease of the inner ear (labyrinth) that is characterized by fluctuating sensorineural hearing loss; tinnitus; episodic vertigo; and aural fullness. "Second, increased amounts of anti-IGHG1 antibodies in patients with Meniere's disease may be a result of an excessive autoimmune or inflammatory reaction in the inner ear." (PMID 25330336, 2014).
renal carcinoma (1 paper, 2025). A carcinoma arising from the epithelium of the renal parenchyma or the renal pelvis. "Most surprisingly, the high ratio of IGHA1 to IGHG1 very strongly correlated with prolonged survival in renal cancer." (PMID 40990023, 2025). "Additionally, in renal cancer, high IGHA1/IGHG1 ratios were linked to worse survival." (PMID 40990023, 2025).
salivary gland tumors (1 paper, 2024). "Some of the identified peptides were derived from proteins previously suggested as potential biomarkers of salivary gland tumors (ANXA1, BPIFA2, FGB, GAPDH, HSPB1, IGHG1, VIM) or tumors of other tissues or organs (SERPINA1, APOA2, CSTB, GSTP1, S100A8, S100A9, TPI1)." (PMID 39201484, 2024).
sarcoma (1 paper, 2011). A usually aggressive malignant neoplasm of the soft tissue or bone. "The mRNA of the constant region segments of both IGHG1 and kappa light chains were detected in these sarcoma cell lines." (PMID 21731691, 2011).
Sepsis (1 paper, 2025). Sepsis is defined as life-threatening organ dysfunction caused by a dysregulated host response to infection. "Furthermore, several immunoglobulin genes including membrane and secreted forms of IGHM, IGHG1 and IGHG2 were also reduced in sepsis patients." (PMID 41208955, 2025).
triple-negative breast carcinoma (1 paper, 2023). An invasive breast carcinoma which is negative for expression of estrogen receptor (ER), progesterone receptor (PR), and human epidermal growth factor receptor 2 (HER2). "Conversely, high expression of IGHG1 was correlated with recurrence and functioned as a tumor suppressor in triple-negative breast cancer." (PMID 36752296, 2023).
type-1 diabetes (1 paper, 2025). "For CD2 and CD3, the human genes of S100A9 (calcium binding protein A9) and IGHG1 (immunoglobulin heavy constant gamma 1) have previously identified as genes of interest as is the case with REG1A (pancreatic stone protein) for type-1 diabetes." (PMID 40893175, 2025).
tumor (55 papers, 2007 to 2025). "A unique tumor cluster was identified in the metastatic sample that strongly expressed metastasis-associated marker IGHG1, which encodes a factor that promotes oncogenesis and progression." (PMID 41279557, 2025). "For instance, the denoised data indicated substantial enrichment of IGHG1 in clusters associated with tumor edges (Clusters 10, 14, 16, and 18), which closely aligned with the manually annotated tumor edge regions." (PMID 40179332, 2025). "High IGHG1 expression was, however, significantly associated with tumor diameter, pathological stage, pathological grade, and progesterone receptors (P < 0.05)." (PMID 36883223, 2023). "The data further indicate that the expression levels of IGHG1 mRNA are more associated with an active immune response in the tumor than IGHA2 mRNA." (PMID 32656317, 2020). "Intriguingly, IGHG1 expression in B-cells and plasma cells could be associated with immune evasion and tumor cell proliferation in breast malignancies." (PMID 36497286, 2022). "IGHG1 mRNA levels were also more correlated with metagenes associated with an immune response which makes it conceivable that the IgG production, more than IgA production, reflects an active immune response in a tumor." (PMID 32656317, 2020). "Several studies have demonstrated that high IGHG1 expression promotes tumor proliferation, migration, and invasion, and correlates with poor prognosis." (PMID 41149858, 2025). "In vitro cytotoxicity assay showed that IGHG1 can competitively bind to Fcγ receptors (FcγR) on the surface of NK cells, and assist immune escape of tumor cells by blocking the activity of NK cells to downregulate the ADCC effect." (PMID 40535807, 2025). "In contrast, lymph node metastases displayed a unique tumor cell phenotype marked by IGHG1 expression, and the microenvironment was immunosuppressive resulting from activation of the TGFβ signaling pathway, potentially inducing immune exhaustion." (PMID 41279557, 2025). "B cells from COPD and cancer shared biological functions, and tumor‐infiltrating B cells overexpressed genes (IGHG1‐4, IGKC, IGHA1) consistent with COPD." (PMID 41377765, 2025). "Our observations revealed IGHG1+ plasma cells scattered within the tumor area, with CCL19 exhibiting high expression levels around these plasma cells, suggesting its role as a supportive component for plasma cells." (PMID 39505867, 2024). "Our observations revealed CD3D+ T cells accumulating in clusters within the tumor area and tumor boundary, with IGHG1+ plasma cells and CCL19+ fibroblasts scattered within these T cell clusters." (PMID 39505867, 2024). "We noted that the genes upregulated in PCC cells almost always showed positive correlations with clinical parameters, especially IGHG1 (P < 0.05, with T stage, pathological stage, and tumor grade)." (PMID 38898490, 2024). "The CosMx data also revealed that C1QC+ macrophages, CCL5+ T cells, and IGHG1+ plasma cells were more abundant near one tumour subclone while COL3A1+ fibroblasts were more abundant near the other." (PMID 38570491, 2024). "The tumor proliferation marker, Ki-67, and IGHG1 levels were assessed by hematoxylin eosin (H&E) staining and IHC." (PMID 36883223, 2023). "Meanwhile, inhibition of IGHG1 restrained the tumor growth in nude mice and inactivated MEK/ERK/c-Myc pathway." (PMID 34315496, 2021). "Results also demonstrated that IGHG1 protein was significantly elevated in tumor samples (p < 0.001)." (PMID 34315496, 2021). "As a result, tumor cells with IGHG1 overexpression vector transfection exhibited significantly enhanced wound gap healing capacity compared with control group, and vice versa." (PMID 34315496, 2021).
tumor (continued). "To further unveil potential modulative impact of IGHG1 on tumor cell EMT (epithelial-mesenchymal transition), we utilized western blot and qRT-PCR method to detect several EMT markers (N-cadherin, Vimentin, E-cadherin)." (PMID 34315496, 2021). "Results suggested that IGHG1 was significantly elevated in all tumor cell lines (MKN45, HGC27, MGC-803, BGC-823, AGS, MKN28), in comparison with normal gastric epithelial cell line GES-1." (PMID 34315496, 2021). "The expression level of IGHG1 was negatively correlated with tumor purity (r = −0.610, p < 0.001), but it was positively correlated with the stromal score (r = 0.570, p < 0.001), ESTIMATE score (r = 0.610, p < 0.001), and immune score (r = 0.610, p < 0.001)." (PMID 34760705, 2021). "Functional assays including CCK8 assay, Edu assay, sphere formation assay and transwell assay, wound healing assay, etc. were subsequently performed to evaluate the impact of IGHG1/-catenin axis on tumor cell proliferation, migration and chemo-resistance." (PMID 34315496, 2021). "Previous studies indicated that IGHG1 as well as -Catenin serve as important regulators of tumor cellular malignancy." (PMID 34315496, 2021). "As expected, we observed an increase in the levels of markers that are important for immune responses and inflammation (Saa1, Saa2, Lcn-2, Ltf, and Orosomucoid-2) and initiating and promoting tumor growth (Ighg1, Scube3, and Fgl1)." (PMID 33110211, 2020). "Inhibition of IGHG1 restrained the tumor growth in nude mice and inactivated MEK/ERK/c-Myc pathway both in vitro and in vivo." (PMID 31355278, 2019). "ARHGAP21 and IGHG1 were strongly expressed in both stromal and tumor cells, and therefore excluded from further study." (PMID 31533654, 2019). "Our previous study demonstrated that HeLa cells stably expressing IgG grew faster than IGHG1 shRNA-treated cells in vitro and in vivo, indicating that cancer-derived IgG can promote tumor cell growth and proliferation." (PMID 25179302, 2014). "The results showed that IgGγ expressions of tumor tissues from group 3 (IGHG1 shRNA) or 4 (IGHG1 shRNA with LPS treatment) were lower than that from group 1 (Control shRNA) or 2 (Control shRNA with LPS treatment) at both protein and mRNA levels." (PMID 25179302, 2014). "The tumor-associated proteins identified in study, PDIA6, MEG3, SDCCAG3, IGHG1 and IGHG3 have been previously reported to have cancer-associated properties." (PMID 23977302, 2013). "Notably, IGHG1 demonstrated high expression levels at the tumor boundary of immune exclusion samples, suggesting a potential mechanism wherein tumor cells impede the infiltration of plasma cells." (PMID 39505867, 2024). "A 6-fold reduction in tumor size and weights were observed in the IGHG1-knockdown group." (PMID 36883223, 2023). "Reclustering revealed 11 distinct subclusters, of which nine were enriched in tumor and interface zones and designated as plasma B cells (clusters 2 and 10, IGHG1 +), follicular B cells (clusters 0, 3, 6, 8 and 9, MS4A1 +), immature B cells (cluster 7, IL7R +) and mast cells (cluster 5, TPSAB1 +)." (PMID 37644609, 2023). "We then analyzed and marked the top 20 DEG genes in tumor core regions and found that IGHG1, IGHG3, IGHG4, IGKC, and IGLC2 (effector markers for humoral immunity) were notably downregulated in core regions, possibly indicating an immunosuppressive microenvironment (ISME)." (PMID 35673582, 2022). "Moreover, chemo-resistance assay on MKN45 cell groups indicated that tumor cells transfected with IGHG1 overexpression vector demonstrated enhanced chemo-resistance compared with control cell group, under the challenges of three chemo-agents." (PMID 34315496, 2021). "And IGHG1 silencing by shRNA transfection drastically suppressed tumor cell migration and invasion." (PMID 34315496, 2021). "Moreover, sphere formation assay provided consistent evidences that IGHG1 overexpression considerably increased tumor cell sphere formation compared with control group, and vice versa." (PMID 34315496, 2021).